DOT1L (DOT1 like histone lysine methyltransferase)
Diseases named in the same sentence as DOT1L in open-access papers (continued):
Sharing a sentence is not in itself a finding about the gene and the disease.
leukemia (continued). "Genetic or pharmacological inhibition of DOT1L leads to downregulation of target genes and impaired proliferation, cell cycle, and survival of leukemia cells in leukemias driven by MLL fusion." (PMID 35712672, 2022). "In MLLT10-rearranged leukemia, DOT1L induces the transcription of genes involved in cell cycle progression (especially genes in the Homeobox A Cluster)." (PMID 36158701, 2022). "The suppression of RNF20 in diverse models of MLL-rearranged leukemias resulted in reduced H3K79 methylation by DOT1L and the inhibition of cell proliferation, suggesting that reducing RNF20-mediated H2B ubiquitination induces an antileukemic effect." (PMID 35331314, 2022). "Selective drugs developed to restrain the proliferation of MLL-r leukemia cells through inhibiting DOT1L due to the ability of inducing the hyperexpression of HOXA9 and MEIS1." (PMID 36376832, 2022). "It is possible that the crosstalk between PKM2-catalyzed H3pT11 and DOT1L-catalyzed H3K79me3 plays a role in leukemia." (PMID 36473858, 2022). "Overall, recent research has expanded the utility of DOT1L inhibition in leukemias outside MLLr and points to combination therapy involving DOT1L as promising in development of novel targeted therapies." (PMID 35712672, 2022). "Recent advancements in small molecule degraders encouraged us to explore the design of an effective PROTAC or molecular glue to degrade DOT1L as an alternative approach to enzymatic inhibitors in MLL-rearranged leukemias." (PMID 35331314, 2022). "We hope that this study will provide valuable guidance for DOT1L-associated drug development and future clinical treatments of MLL-rearranged leukemias." (PMID 35331314, 2022). "SGC0946, a brominated analogue of EPZ004777, inhibit DOT1L in vitro and selectively kill mixed lineage leukaemia cells." (PMID 36376832, 2022). "Understanding the detailed mechanisms of their cross talk, including DOT1L regulation through histone acetylation and ubiquitination, would contribute to targeting DOT1L in MLL-rearranged leukemias." (PMID 35331314, 2022). "To showcase potential application in such scenarios, we tried knocking-down DOT1L in MV4-11 leukemia cells." (PMID 36185457, 2022). "DOT1L is involved in tumorigenesis and tumor metabolism or metastasis of ovarian cancer, prostate cancer, leukemia, neuroblastoma, colorectal cancer, and breast cancer." (PMID 34395285, 2021). "While the pre-clinical studies showed promising activity of DOT1L inhibitors, the phase I study of DOTlL inhibitor, pinometostat, in adult and pediatric patients with relapsed or refractory leukemia demonstrated limited clinical response." (PMID 33879235, 2021). "Particularly, DOT1L has a well-established role in MLL-fusion leukemia, in which DOT1L is targeted to promoters of genes important for disease initiation and progression, including HOXA9 and MEIS1." (PMID 35201498, 2021). "More recently, several MLL-rearranged leukemias were shown to be dependent on the only known histone 3 lysine 79 (H3K79) methyltransferase DOT1L." (PMID 34068470, 2021). "Preclinical models demonstrate that MLL-driven leukemia is particularly sensitive to inhibition of DOT1L activity, and DOT1L inhibitors have been shown to specifically reduce H3K79 methylation marks and expression of MLL-fusions target genes in leukemic cells." (PMID 33879235, 2021). "EPZ-5676 is a highly selective and potent DOT1L inhibitor with proven efficacy in MLL-rearranged leukemia and is under clinical investigation." (PMID 34253709, 2021). "RNA-sequencing was performed to investigate how 1-mediated disruption of the PPIs between AF9/ENL and DOT1L or AF4/AFF4 affects global gene expression in MLL-r leukemia." (PMID 34373735, 2021). "For this purpose, we established, characterized, and used MLL-AF9 transformed leukemia cell lines transduced with several different DOT1L constructs, including wild type and mutants, to disrupt either PPIs or enzymatic activity." (PMID 33562706, 2021).
leukemia (continued). "Formation of AF9/ENL/AF4/AFF4-containing super elongation complexes (SEC) and the catalytic activity of DOT1L are essential for MLL-rearranged leukemia." (PMID 34373735, 2021). "DOT1L was identified to promote MLL-rearranged leukemia by interacting with various MLL-fusion proteins and thereby aberrantly upregulating the expression of MLL target genes." (PMID 34887387, 2021). "The upregulation of HOXA genes in CALM-AF10 leukemia is dependent on AF10’s recruitment of DOT1L, and resultant focal H3K79 hypermethylation specifically at the HOXA locus." (PMID 35070954, 2021). "We show that the interaction between AF9 and DOT1L is critical for MLL-AF9 driven leukemia and blocking this PPI inhibits H3K79 methylation at MLL-target genes." (PMID 33562706, 2021). "The findings of this study provide further evidence validating the rationale for a novel promising strategy that disrupts interactions between DOT1L and AF9 in MLL fusion protein-associated leukemia." (PMID 33562706, 2021). "This study demonstrates the therapeutic potential of DOT1L in the mixed lineage leukemia (MLL) gene rearrangement of leukemia and lays the foundation for future combination therapy in this patient population (NCT01684150)." (PMID 34149432, 2021). "DOT1L is a therapeutic target for MLL-r leukemia: genome-wide hypermethylation of H3K79 is characteristic to the cancer 24 and DOT1L's catalytic activity is required for expression of MLL-target genes, such as HoxA9 and Meis1." (PMID 34373735, 2021). "In a document published in 2019, it has been confirmed that pinometostat as a DOT1L inhibitor has entered a phase 1 clinical trial to treat children with relapsed/refractory leukemia with MLL gene rearrangement Patient (NCT02141828)." (PMID 34149432, 2021). "Control leukemia cells expressing WT-DOT1L showed rescue of proliferation, confirming that the observed phenotype was due to loss of DOT1L and its histone methyltransferase activity." (PMID 33562706, 2021). "It is undeniable that effective inhibitors of DOT1L have achieved many surprising results in targeting leukemia with MLL gene rearrangement." (PMID 34149432, 2021). "NF-κB activation correlates with DOT1L activation which has been shown to be required for development of MLL-rearranged leukemias." (PMID 34736527, 2021). "Pharmacological inhibition of the PPIs significantly reduced SEC and DOT1L-mediated H3K79 methylation in the leukemia cells." (PMID 34373735, 2021). "Inhibition of DOT1L activity or disruption of DOT1L interaction with MLL fusion partners are potential therapeutic strategies for the treatment of rearranged MLL leukemia." (PMID 34500733, 2021). "Subsequent studies of the effect of DOT1L inhibitors in patients with MLL-rearranged leukemia had promising results." (PMID 34253709, 2021). "DOT1L's catalytic activity is required for the aberrant gene expression and leukemia transformation." (PMID 34373735, 2021). "We further propose that targeting these PPIs will offer therapeutic advantages over enzymatic inhibition of DOT1L in MLL-rearranged leukemia, which globally effects gene expression of which the long-term effects are not yet clear." (PMID 33562706, 2021). "Rather, our results here show that DOT1L/H3K79 methylation in MLL-r leukemia cells is directed by AF9/ENL or more likely, AF9/ENL-containing SEC." (PMID 34373735, 2021). "The aberrant methylation of H3K79 by DOT1L would enhance the expression of leukemogenic genes homeobox A9 (HOXA9) and Meis Homeobox 1 (MEIS1), driving the pathogenic of mixed lineage leukemia (MLL) rearranged leukemia." (PMID 34425876, 2021). "Recent studies have elucidated the role of the histone methyltransferase disrupter of telomeric silencing 1-like (DOT1L) in MLL-r leukemias." (PMID 32698374, 2020). "In MLL-rearranged leukemia, DOT1L is thought to maintain expression of leukemia stem cell genes through recruitment via MLL fusion proteins to these gene loci, leading to higher H3K79me2 levels." (PMID 32215184, 2020).
leukemia (continued). "In leukemia cells, it was shown that inhibition of DOT1L, the sole human homolog of yeast Dot1, and H3K79 methylation increased apoptosis due to downregulation of the antiapoptotic protein BCL2L1." (PMID 33255318, 2020). "Two classes of small molecule inhibitors have emerged as possible therapies for KMT2A-rearranged leukemia: Disruptor of telomeric silencing 1-like (DOT1L) inhibitors and menin inhibitors." (PMID 32050659, 2020). "Nevertheless, the dependency of the MLL fusion-driven gene expression program on the DOT1L pathway provides potential therapeutic opportunities for MLL leukemia." (PMID 32552847, 2020). "Based on these actions, some compounds, such as EPZ004777 and EPZ5676, that target the catalytic activity of DOT1L have been developed for the treatment of MLL-induced leukemia as well as other solid tumors." (PMID 33363525, 2020). "The histone 3 lysine 79 (H3K79) methyltransferase disruptor of telomeric silencing-1 like (DOT1L) is proposed to play a role in the development of leukemia in patients with MLL translocations." (PMID 32690020, 2020). "As already explained, DOT1L is responsible for H3K79 methylation in leukemia carried out by MLL-FP complexes." (PMID 33302406, 2020). "Pharmacological inhibition of DOT1L enzymatic activity has been of interest for the treatment of MLL-rearranged leukemias." (PMID 32690020, 2020). "It is of interest that DOT1L can also be targeted in the leukemias devoid of KMT2A rearrangements —or, even, in the KMT2-unrelated solid tumors—to suppress the proliferation and metastasis of breast cancer cells." (PMID 33302406, 2020). "The specificity of this RNA-protein interaction was further verified by RNA immunoprecipitation (RIP) of DOT1L-FLAG in MLL leukemia cell lines." (PMID 32552847, 2020). "As a result, in MLL-r leukemias, DOT1L is recruited on ectopic target sites, and its mislocation promotes the aberrant overexpression of developmentally important genes—for instance, HOXA cluster genes and MEIS1." (PMID 32698374, 2020). "Accordingly, the DOT1L inhibitor Pinometostat was evaluated in phase I clinical trials enrolling both pediatric or adult patients with MLL-r leukemias." (PMID 32698374, 2020). "Multiple aberrations in histone PTMs have been observed in leukemias and lymphomas, such as EZH2 mutations altering H3 K27 methylation, DOT1L dysregulation of H3 K79 methylation with MLL translocations, and KMT2D mutations affecting H3 K4 methylation." (PMID 33104722, 2020). "DOT1L is associated with the development and maintenance of MLL-rearranged leukemias and potent inhibitors have been reported." (PMID 31817960, 2019). "MLL1 fusions have been shown to recruit DOT1L, a histone 3 lysine 79 (H3K79) methyltransferase and epigenetic marker of leukemic stem cells which has been implicated in the development of leukemia." (PMID 30548174, 2019). "MLL-R leukemias are uniquely dependent on the epigenetic function of the H3K79 methyltransferase DOT1L, which is misdirected by MLL-FPs activating gene expression, driving transformation and leukemogenesis." (PMID 31717699, 2019). "The resulting fusion of the MLL gene promotes recruitment of the lysine methyltransferase DOT1L to methylate histones at pro-leukaemia genes and drive aberrant gene transcription." (PMID 31791394, 2019). "In leukemia, DOT1L forms a protein complex with the mix lineage leukemia (MLL) fusion proteins and mediates H3K79 methylation, which is responsible for maintaining an open chromatin state around MLL fusion protein to target oncogenes." (PMID 31888761, 2019). "The aberrant upregulation of H3K79 methylation in leukemia led to the development and use of DOT1L inhibitor EPZ-5676 for the treatment of MLL-rearranged leukemia which is currently under clinical investigation." (PMID 31747960, 2019). "In MLL‐r leukemia, DOT1L recruitment to MLL target genes, such as the HoxA cluster, leads to aberrant H3K79 methylation and increased transcription." (PMID 31304633, 2019).
leukemia (continued). "We found that the DOT1L inhibition impairs the proliferation of MLL-AF9 leukaemia cells, as previously reported." (PMID 31882723, 2019). "The recent clinical trials for the treatment of MLLr leukaemia with the inhibitor of DOT1L EPZ5676 are starting to address this question." (PMID 31791394, 2019). "The histone H3K79 methyltransferase DOT1L (KMT4; Dot1 in yeast) is an epigenetic enzyme for which inhibitors are in clinical development for the treatment of MLL‐rearranged (MLL‐r) leukemia." (PMID 31304633, 2019). "Small molecule-mediated DOT1L inhibition proved to be a promising strategy in leukemia with MLL-fusion proteins." (PMID 30818762, 2019). "The ability of MLL-FPs to reprogram HSPCs toward leukemia requires the involvement of multiple chromatin effectors, including the histone 3 lysine 79 methyltransferase DOT1L, the chromatin epigenetic reader BRD4, and the super elongation complex." (PMID 31157223, 2019). "Because the aberrant methyltransferase activity of DOT1L is required for the leukemogenesis of MLL-r leukemia, DOT1L inhibition is a promising therapeutic intervention (Chang M.-J." (PMID 31157223, 2019). "Most promisingly, perturbation of Met/SAM metabolism in either MLL-R cell line potently reduced global levels of H3K79me2, the DOT1L catalyzed activating modification absolutely required by MLL-R leukemia for survival and maintenance of malignant potential." (PMID 31717699, 2019). "Some of the MLL-rearranged (MLL-r) leukemia genes are modulated through hypermethylation by DOT1L of a set of genes that elicit leukemogenesis." (PMID 31727944, 2019). "It was reported that 5-aza-C and DOT1L inhibitor EPZ-5676 synergistically inhibited the proliferation of leukemia cells with MLL abnormalities." (PMID 31527484, 2019). "Recent studies have uncovered a role for DOT1L in the initiation and progression of leukemia and other solid tumors." (PMID 30616689, 2019). "Using the DOT1L inhibitor EPZ-5676 in MLL-AF4 leukemia cells, we show that H3K79me2/3 is required for maintaining chromatin accessibility, histone acetylation and transcription factor binding specifically at KEEs but not non-KEE enhancers." (PMID 31243293, 2019). "In recent years, there has been a focus on the role of the protein methyltransferase DOT1L in MLL-fusion-transformed leukaemias." (PMID 31882723, 2019). "We observed Menin-MLL and DOT1L inhibitors act very specifically on MLL-fused leukemia cell lines, whereas inhibitors of BET, DHODH and P-TEFb have strong effects beyond MLL-fusions." (PMID 31253180, 2019). "Recently developed small molecule inhibitors of DOT1L are currently being tested in the treatment of MLL-rearranged leukemia." (PMID 30616689, 2019). "The DOT1L dependency of the thymic lymphomas resembles that of MLL‐rearranged leukemia as well as breast and lung cancer cell lines." (PMID 31304633, 2019). "Study shows that leukemia cells with MLL fusion genes are hypersensitive to DOT1L inhibitors such as EPZ5676." (PMID 31590683, 2019). "We used the small-molecule DOT1L inhibitor EPZ-567639 to diminish H3K79me2/3 genome wide in SEM (MLL-AF4) leukemia cells." (PMID 31243293, 2019). "Inhibitors have been developed to target DOT1L activity in leukemia, but cellular mechanisms that regulate DOT1L are still poorly understood." (PMID 31304633, 2019). "Here, we demonstrate that, in contrast to MLL-rearranged leukemia, DOT1L plays a protective role in ultraviolet radiation (UVR)-induced melanoma development." (PMID 29343685, 2018). "Taken together, the different pattern of DOT1L/H3K79me2 in melanoma vs. leukemia cells suggest a different role of DOT1L/methylated H3K79 in melanoma compared to leukemia." (PMID 29343685, 2018). "We analyzed the data from the other study and identified 1508 genes whose gene body regions contain sites with significantly decreased H3K79me2 levels in the DOT1L inhibitor-treated leukemia cell line MV411." (PMID 29343685, 2018).
leukemia (continued). "The example of DOT1 L in MLL-r leukaemia involves an indirect role of a chromosomal rearrangement affecting the activity of a PMT." (PMID 29685962, 2018). "We found that 406 DOT1L-target genes (~27% for either melanoma or leukemia) are shared between the melanoma and leukemia cell lines." (PMID 29343685, 2018). "Such is the case for the enzyme DOT1 L in a form of acute leukaemia known as MLL-rearranged (MLL-r) leukaemia." (PMID 29685962, 2018). "It is worth noting that DOT1L is extremely important in development and a large proportion of MLL-linked leukaemia patients are infants, making alternative treatment options all the more important." (PMID 29495487, 2018). "DOT1L inhibition is beneficial in MLL-fusion-induced leukemia and DOT1L inhibitors (DOT1Li) are under investigation in a phase 1 clinical trial in patients with this pathology." (PMID 29721185, 2018). "Simultaneous inhibition of MENIN-MLL interaction and DOT1L HMT activity synergistically induces differentiation of MLL fusion-associated leukemia cells, supporting the notion that the MLL fusion complex and the DOT1L complex collaborate to induce leukemia." (PMID 30693017, 2018). "DOT1L is also an important drug target for treatment of mixed lineage leukemia (MLL)-rearranged leukemia where aberrant transcriptional activation is promoted by DOT1L mislocalisation." (PMID 29495487, 2018). "It has also been reported that aberrant H3K79 methylation by DOT1L occurs in Mixed Lineage Leukemia (MLL)." (PMID 28837080, 2017). "DOT1L inhibitor EPZ-5676 was also able to establish a chromatin state that enhanced the anti-tumor effects of cytarabine or daunorubicin in MLL-rearranged leukemia." (PMID 28148257, 2017). "Continuous infusion of DOT1L inhibitors significantly prolonged the OS in murine models with MLL leukaemia, leading to the first clinical trial of HMT inhibitors in AML." (PMID 27593928, 2017). "It is interesting to note that small molecule DOT1L inhibitors have been recently developed, and one of the DOT1L inhibitors is already under investigation in a phase I clinical trial in patients with MLL fusion gene-driven leukemia." (PMID 28114995, 2017). "Aberrant recruitment of DOT1L specifically associates with an abnormally high level of H3K79me2 on promoters and gene bodies of MLL targets in MLL-rearranged leukaemia." (PMID 27593928, 2017). "DOT1L is well-known to be associated with pathological functions where interactors recruit DOT1L to specific gene regions, like in MLL-rearranged leukemias which present abnormal H3K79 methylation pattern at HOX loci." (PMID 28804523, 2017). "The DOT1L protein is essential for the growth of MLL-rearranged leukemia cells and exerts its effect by maintaining active transcription of Hoxa9 and Meis1." (PMID 28231254, 2017). "In human, DOT1L is involved in the oncogenesis of several leukemia subtypes, mostly characterized by chromosomal translocations involving the mixed lineage leukemia (MLL) gene." (PMID 28114995, 2017). "Treatment of MLL-rearranged leukemia with EPZ00477 or EPZ-5676 (potent and selective amino nucleoside inhibitors of DOT1L histone methyltransferase activity) causes cell death in acute leukemia lines bearing MLL translocations." (PMID 28837080, 2017). "We used this approach to identify novel resistance alleles of two lysine methyltransferases, DOT1L and EZH2, which are each essential for the growth of MLL-fusion leukemia cells." (PMID 28231254, 2017). "Targeting selective histone methyltransferase is a promising approach, and DOT1L inhibitors are in clinical trials for leukemias with MLL rearrangements." (PMID 28804523, 2017). "H3K79 methylation by DOT1L is associated with transcriptional activation of genes under its regulation, and overexpression or aberrant DOT1L activity has been found in cancer, such as leukemia with mixed lineage leukemia (MLL) gene translocation." (PMID 28148257, 2017).